ENSG00000275372
Gene: Miscellaneous RNA gene on chromosome 2 (144,518,447 to 144,518,574, forward strand). Ensembl gene ENSG00000275372.
Gene Ontology:
Biological process: positive regulation of gene expression
Homologues: Orthologues: mouse Gm56475 (91% identical).